TNF (tumor necrosis factor)
Diseases named in the same sentence as TNF in open-access papers (continued):
Sharing a sentence is not in itself a finding about the gene and the disease.
neurodegenerative disease (continued). "For example, in neurodegenerative disease, exosomes derived from Aβ- or alpha-synuclein-activated microglia deliver misfolded proteins and membrane tumor necrosis factor alpha (TNF-alpha) to neurons, which cause neuronal dysfunction and death." (PMID 35634460, 2022). "Crucial in the pathogenesis of neurodegenerative diseases is the process of neuroinflammation that is often linked to the pro-inflammatory cytokines Tumor necrosis factor alpha (TNFα) and Interleukin-1beta (IL-1β)." (PMID 35625761, 2022). "Neurodegenerative diseases like AD are associated with increased neuroinflammatory markers (e.g., IL-1β and TNF-α) and loss of synaptic markers (e.g., synaptophysin and drebrin)." (PMID 35742911, 2022). "Elevated levels of LPS and TNFα have been associated with neurodegenerative diseases together with reduced levels of AA." (PMID 34285658, 2021). "Elevated levels of TNF are observed in autoimmune and degenerative diseases and deregulated TNF expression and signaling has been implicated in the pathology of many inflammatory diseases." (PMID 34305946, 2021). "Kopp conducted the most recent cohort study to assess the risk of developing neurodegenerative diseases in arthritis patients treated with anti-TNF drugs." (PMID 34804701, 2021). "In particular, IL-1β, IL-6, and TNF-α are representative pro-inflammatory cytokines associated with various degenerative diseases." (PMID 34234892, 2021). "Microglia have been implicated as major producers of TNF-α in neurodegenerative diseases and CNS injuries." (PMID 32938988, 2020). "TNF-α and IL-1β are typical proinflammatory cytokines associated with degenerative diseases, and they induce inflammatory disease by affecting the synthesis of mediators such as PG, leukotriene, and NO." (PMID 31635294, 2019). "On the other hand, estrogen deficiency is associated with the increase in proinflammatory cytokines, such as interleukin (IL)-1, IL-6, and tumor necrosis factor-α, which is linked to the development of AD or neurodegenerative disease." (PMID 31885921, 2019). "On the other hand, high levels of pro-inflammatory cytokines (IL-6 and TNF) cause damage to the microglia promoting autoimmune and neurodegenerative diseases." (PMID 31694049, 2019). "The discovery of the apparent dual role of TNF through its two receptors has initiated extensive research into new possibilities to treat neuroinflammation, a common hallmark of neurodegenerative diseases." (PMID 30778285, 2019). "Activation of microglial cells results in the production of major proinflammatory cytokines, TNF-α and IL-6, during CNS inflammation, which is typically associated with neurodegenerative diseases including AD." (PMID 31057649, 2019). "As proinflammatory and neuro-toxic cytokines, IL-1β and TNF-α are secreted by M1 phenotype microglia and cause neuronal cell death in most neurodegenerative disease." (PMID 30607245, 2018). "In this study, we employed a DNA-aptamer that was able to recognize the tumor necrosis factor-alpha (TNFα), a primary pro-inflammatory cytokine that plays a crucial role in enhancing the immune response associated with degenerative diseases." (PMID 30544583, 2018). "TNF-α produced very marked hypothermia, weight loss and suppression of activity in animals with existing neurodegenerative disease, with respect to normal healthy animals similarly challenged." (PMID 27633985, 2017). "Pro-inflammatory cytokines, which include IL-1β, IL-6, and TNF-α, are believed to moderate neuroinflammation and cause cell death in different neurodegenerative diseases." (PMID 28490320, 2017). "Elevation of TNFα and IL-1β is a hallmark of neuroinflammation, which is a critical etiology in neurodegenerative diseases." (PMID 28103888, 2017). "TNF-α has been implicated as an important factor for the onset and perpetuation of neurodegenerative diseases, since increased levels of this cytokine are present in the affected areas in many neurodegenerative diseases." (PMID 27075886, 2016).
neurodegenerative disease (continued). "Many studies demonstrated that some of the proinflammatory cytokines, such as TNF-α, IL-1β, and IL-6, play a key role in the development and maintenance of inflammation, and this cytokine elevation is associated with neurodegenerative diseases." (PMID 25157358, 2014). "Pro-inflammatory genes and cytokines such as TNFα, IL-1 and IL-6 are associated with human neurodegenerative diseases." (PMID 23675513, 2013). "Different groups have demonstrated that the inflammatory cyclooxygenase-2 (COX-2), inducible nitric oxide synthase (iNOS) and cytokines, such as interleukin (IL)-1β, IL-6 and tumor necrosis factor (TNF)-α, are associated with neurodegenerative diseases." (PMID 22214188, 2012). "BBB damage has been seen in many neurodegenerative diseases and animal models of seizure, and studies have shown that pro-inflammatory cytokines including TNF-α, IL-1β, IL-6, and interferon-λ are implicated in the regulation of BBB permeability." (PMID 21777430, 2011). "We chose to analyze sTNFR-1A because it is an important mediator of TNF signaling in the brain, it is suspected to play a role in a number of neurodegenerative diseases and is implicated in inflammatory processes." (PMID 20436668, 2010). "Pro-inflammatory cytokines, in particular TNF, exert potent toxic effects on dopaminergic neurons and have been implicated in neurodegenerative disease pathogenesis." (PMID 18474101, 2008). "TNF‐α is a key inflammatory cytokine, playing a role in a multitude of pathogenic processes, ranging from external infections by foreign agents, to diseases caused by the dysregulation of intrinsic cellular mechanisms, such as in neurodegenerative diseases." (PMID 39960781, 2025). "The results from this study may also provide insights into other conditions of the CNS which are associated with chronic neuroinflammation and increased TNF-α and IL-6 concentrations including neurodegenerative diseases and neuropsychiatric conditions." (PMID 40012566, 2025). "Furthermore, pro-inflammatory cytokines such as IL-1β and TNF-α have been implicated in the pathogenesis of neurodegenerative diseases such as experimental autoimmune encephalomyelitis (EAE), multiple sclerosis (MS) and PD." (PMID 39766497, 2024). "TNF-alpha has been implicated in the pathogenesis of AD, PD, and other neurodegenerative diseases." (PMID 38891863, 2024). "Pro-inflammatory factors such as TNF-α, IL-6, and IL-1β, released by activated microglia during neuroinflammation, are pivotal in initiating inflammatory responses, regulating cytokine cascades, and being implicated in neurodegenerative diseases." (PMID 39201475, 2024). "Divergent actions of TNF in neurodegenerative diseases have been long implicated." (PMID 35651608, 2022). "The persistent production of proinflammatory mediators or cytokines, such as nitric oxide (NO), cyclooxygenase-2 (COX-2), tumor necrosis factor (TNF)-α, interleukin (IL)-1 and IL-6, exacerbates neuroinflammation, causing neuronal damage and further leading to neurodegenerative diseases." (PMID 36005538, 2022). "Activation of astrocytes and microglias result in the production of major proinflammatory cytokines (TNF-α, IL-6, or IL-1β) and neurotoxic factors (reactive oxidative species and tumor necrosis factor-α), which are typically associated with neurodegenerative diseases including AD." (PMID 32587516, 2020). "Moreover, TNF-a has been shown to induce excitotoxicity-mediated neuronal loss in some neurodegenerative diseases." (PMID 32087723, 2020). "Studies have shown that the activation of microglial cells can be induced by LPS, which produces large amounts of reactive oxygen species (ROS), NO, and proinflammatory cytokines such as IL-6 and TNF-α that damage neurons and ultimately cause neurodegenerative diseases." (PMID 31547327, 2019).
neurodegenerative disease (continued). "As a prolonged or chronic inflammatory response can induce an environment that is susceptible to dysfunction, TNF-α may be an ideal drug target as a treatment strategy to mitigate neurodegenerative diseases." (PMID 31867326, 2019). "This concluded that JNK/NF-κB/TNF-α-mediated cross-talk in the activated microglia is the major underlying reason for neuronal death through the activation of the Bcl-2 gene family in various neurodegenerative diseases." (PMID 28671636, 2017). "TNF-α is a proinflammatory cytokine that is released in large amounts by microglia in pathological conditions, and this de novo production is considered to be an important feature of neuroinflammatory response associated with neurodegenerative diseases." (PMID 29218049, 2017). "We propose that the excess levels of TNF, and glutamate in the brain across a range of neurodegenerative diseases are crucially linked, high TNF causing extracellular glutamate to accumulate to levels high enough to inhibit synaptic activity and kill neurons by two synergistic mechanisms." (PMID 27596607, 2016). "TNF, in particular, has been implicated as an important factor for the onset and perpetuation of neurodegenerative diseases, since increased levels of this cytokine are present in the affected areas in many neurodegenerative diseases." (PMID 25834699, 2015). "Given the elevated levels of TNF-α in the brains during various neurodegenerative diseases, neuronal cells may be susceptible to necroptosis upon stimulation of TNF-α, therefore contributing to the pathogenesis of neurodegenerative diseases." (PMID 25093162, 2014). "Systemic inflammation might cause neuronal damage and sustain neurodegenerative diseases and behavior impairment, with the participation of pro-inflammatory cytokines, like tumor necrosis factor (TNF)-α and interleukin (IL)-18." (PMID 22642744, 2012). "Thus, elevated activity and/or expression of iNOS, COX-2, MMP-9, IL-1β and TNF-α in brain cells have been implicated in the cascade of events leading to neurodegenerative diseases." (PMID 22018032, 2011). "Under conditions of neurodegenerative diseases, ROS activates the transcription factor NFκB in glial cells, causing it to transfer from the cytoplasm to the nucleus, thereby promoting the transcription of some important pro-inflammatory genes, including IL-1β, IL-6, and TNF-α." (PMID 40699625, 2025). "Microglia activated by LPS stimulation led to the production of proinflammatory cytokines and mediators, such as TNF-α, IL-6, and IL-1β, and their chronic increase predisposes the CNS to neuroinflammation, which may result in the development of neurodegenerative diseases, such as AD." (PMID 40720378, 2025). "However, in the case of neurodegenerative diseases, activated microglia cause the production and release of pro-inflammatory mediators such as nitric oxide (NO), interleukin (IL)-1β, IL-6, and tumor necrosis factor (TNF-α)." (PMID 35807828, 2022). "TNF is a pro-inflammatory cytokine produced by microglial cells in response to brain injury, infections, and neurodegenerative diseases such as PD and AD." (PMID 41601963, 2026). "Lowering the levels of TNF-α, IL-6, and IL-1β can prevent the development and progression of inflammatory and degenerative diseases." (PMID 41471283, 2025). "The KEGG pathway enrichment analysis reveals several significantly enriched signalling pathways, including those associated with neurodegenerative diseases, the MAPK signalling pathway, the TNF signalling pathway and more." (PMID 40008552, 2025). "We investigated the effects of SM on IL-1α/TNF-α-induced astrocyte activation, which mimics astrocyte phenotypes in neurodegenerative disease conditions, using HASTR/ci35 cells, a human astrocyte-like cells." (PMID 41192481, 2025).
neurodegenerative disease (continued). "Conversely, astrocytes are abnormally activated by inflammatory cytokines, such as interleukin-1α (IL-1α) and TNF-α, which are released from activated microglia in neurodegenerative diseases that include Alzheimer’s disease and multiple sclerosis." (PMID 41192481, 2025). "NMN has been shown to mitigate these effects by modulating oxidative stress markers (e.g., SOD, CAT) and inflammatory cytokines (e.g., TNF-α, IL-1β, IL-6), thus underscoring its potential in protecting against neurodegenerative diseases." (PMID 40276601, 2025). "Following the DEGs analysis between VGNAs and other cells within their respective clusters, KEGG pathway analysis revealed significant enrichment of pathways related to neurodegenerative diseases, apoptosis, and the TNF signaling pathway in the VGNAs." (PMID 40038739, 2025). "TNF-α, a biomarker of proinflammatory cytokine and neurodegenerative diseases, is secreted by activated astrocytes and microglia." (PMID 40842648, 2025). "An exacerbated expression of pro-inflammatory mediators, such as interleukin 6 (IL-6) and tumor necrosis factor alpha (TNF-α), can characterize the neuroinflammation present in this neurodegenerative disease." (PMID 40648018, 2025). "Pro-inflammatory cytokines, including tumor necrosis factor-alpha (TNF-α), interleukin-1beta (IL-1β), IL-6, and IL-8, have been observed to exacerbate neuronal damage and contribute to the progression of neurodegenerative diseases." (PMID 40309866, 2025). "NF-κB and MAPKs (JNK, ERK, and p38) signaling pathways are pivotal transcription factors for microglial activation and production of cytokines such as IL-1β, IL-6, and TNF-α in various neurodegenerative diseases." (PMID 39764462, 2024). "An in vitro experiment designed to induce chronic exposure to TNF-α in primary porcine RPE cells demonstrated the importance of TNF- α in neurodegenerative diseases such as AMD." (PMID 39062152, 2024). "Elevated markers of brain inflammation such as interleukin (IL)-1β, tumor necrosis factor (TNF), and IL-6 have been found in the CSF, brains, and serum of patients with various neurodegenerative diseases." (PMID 38378578, 2024). "Resveratrol has anti-inflammatory capacity in models of neurodegenerative disease, as shown by its downregulation of tumor necrosis factor α (TNFα) and other proinflammatory molecules." (PMID 38397775, 2024). "In neurodegenerative diseases, microglia contract their protrusions and migrate toward the site of injury, where they release pro-inflammatory cytokines such as IL-1β, TNF-α, and IL-6." (PMID 38649885, 2024). "This process increases the production of pro-inflammatory cytokines like tumor necrosis factor-α (TNF-α) and interleukins (IL-6, IL-1β) in the brain, which are linked to neurodegenerative diseases such as AD and PD." (PMID 39766423, 2024). "TNF-α can be produced by active monocytes and microglia in the course of neurodegenerative diseases." (PMID 38392998, 2024). "Reactive microglia can secrete a broad range of potentially cytotoxic molecules, including NO and TNF, that can contribute to neuronal death observed in neurodegenerative diseases." (PMID 38671980, 2024). "TNF-α, IL-1β, and β-EP play a key role in neurodegenerative diseases, mainly by regulating the release of inflammatory factors from glial cells, and inducing the expression of signaling-related transcription factors." (PMID 36903325, 2023). "Tumor necrosis factor alpha (TNF-α) and its key role in modulating immune responses has been widely recognized as a therapeutic target for inflammatory and neurodegenerative diseases." (PMID 37391534, 2023). "Further investigation is warranted to explore the potential relationship between TNF-α and NF-H levels as indicators of axonal damage and the progression of neurodegenerative diseases." (PMID 37998571, 2023).
neurodegenerative disease (continued). "TNF-α and IL-6 have been found to be involved in the pathogenesis of neurodegenerative diseases, and TNF-α inhibitors are thought to have therapeutic potential in AD by improving cognitive performance." (PMID 37108458, 2023). "Under various neurodegenerative disease conditions, activated microglia release inflammatory cytokines and neurotoxic substances such as IL-1β, IL-6, TNF-α, and nitric oxide (NO), resulting in progressive neuronal degeneration in PD." (PMID 38138478, 2023). "TNF concentrations are elevated after traumatic injury and in several neurodegenerative diseases such as AD, MS, and PD." (PMID 36816125, 2023). "Proinflammatory cytokines, such as TNF-α and IL-6, play a crucial role in mediating the neuroinflammatory response and neurotoxicity in various neurodegenerative diseases." (PMID 37932682, 2023). "We performed RT-PCR to determine the changes in the mRNA expression of pro-inflammatory markers interleukin-1β (IL-1β), tumor necrosis factor-α (TNF-α), interleukin-6 (IL-6), and iNOS based on their potential involvement in neurodegenerative diseases." (PMID 37816735, 2023). "Previous studies have shown that neurodegenerative diseases, including AD, are mediated by inflammation and neurotoxic factors, such as interleukin-1beta (IL-1β), tumor necrosis factor-alpha (TNF-α), reactive oxygen species (ROS), and NFκB activation." (PMID 37056359, 2023). "Both IL-6 and TNF-α are critical pro-inflammatory cytokines in response to LPS, and are considered to be involved in the patho-mechanisms of neurodegenerative diseases." (PMID 37108458, 2023). "The studies on neurodegenerative diseases demonstrated that in the acute phase of inflammation, TNF-α has been complicated in the demyelinating events." (PMID 37427326, 2023). "Pro-inflammatory cytokines, such as TNF-α, IL-6 and IL-1β, play a crucial role in the pathophysiology of neurodegenerative diseases." (PMID 37521470, 2023). "In recent years (2017–2023), physiology, immunology, pathology, degenerative disease, intestine flora, tumor necrosis factor, and effects of action have progressively emerged as the central focus of scholarly researchers." (PMID 38029105, 2023). "TNF helps to regulate immune cell function and plays a pivotal role in the pathogenesis of almost all neurodegenerative diseases." (PMID 36816125, 2023). "The accumulation of visceral fat secretes free fatty acids (FFA), interleukin-6 (IL-6), tumor necrosis factor-alpha (TNF-α) and angiotensinogen into the venous circulation, promoting the formation of heterotopic lipid deposition and degenerative diseases." (PMID 36978933, 2023). "Third, the activation of microglia and astrocytes induced by damage-associated molecular patterns (DAMPs) results in an increased release of the inflammatory cytokines TNF-α, IL-1β and IL-6 in cerebellum, which mediates neurodegenerative diseases." (PMID 37626842, 2023). "The growth of Streptococcus in the gut affects the levels of interleukin-6 and tumor necrosis factor-alpha and contributes to neurodegenerative diseases by inducing neuroinflammation." (PMID 38107849, 2023). "In pathological conditions of neurodegenerative diseases, iron overload triggers microglial polarization to the pro-inflammatory (M1) phenotype via ROS, which increases the secretion of TNF-α and IL-1β and promotes neuroinflammation." (PMID 35342364, 2022). "The same applies to TNFα, which is also contributing to the development of different neurodegenerative diseases." (PMID 35883547, 2022). "Reactive microglia and astrocytes release pro-inflammatory cytokines, such as tumor necrosis factor alpha (TNF-α) and interleukin-1 beta (IL-1β), which leads to glutamate neurotoxicity and neuronal death, events related to neurodegenerative diseases." (PMID 36221097, 2022). "As TNF-α is one of the most extensively studied inflammatory cytokines involved in neurodegenerative diseases." (PMID 36358573, 2022).